AKR1A1 (aldo-keto reductase family 1 member A1)
Description:
Catalyzes the NADPH-dependent reduction of a wide variety of carbonyl-containing compounds to their corresponding alcohols. Displays enzymatic activity towards endogenous metabolites such as aromatic and aliphatic aldehydes, ketones, monosaccharides and bile acids, with a preference for negatively charged substrates, such as glucuronate and succinic semialdehyde. Functions as a detoxifiying enzyme by reducing a range of toxic aldehydes (By similarity). Reduces methylglyoxal and 3-deoxyglucosone, which are present at elevated levels under hyperglycemic conditions and are cytotoxic (By similarity). Involved also in the detoxification of lipid-derived aldehydes like acrolein (By similarity). Plays a role in the activation of procarcinogens, such as polycyclic aromatic hydrocarbon trans-dihydrodiols, and in the metabolism of various xenobiotics and drugs, including the anthracyclines doxorubicin (DOX) and daunorubicin (DAUN). Also acts as an inhibitor of protein S-nitrosylation by mediating degradation of S-nitroso-coenzyme A (S-nitroso-CoA), a cofactor required to S-nitrosylate proteins. S-nitroso-CoA reductase activity is involved in reprogramming intermediary metabolism in renal proximal tubules, notably by inhibiting protein S-nitrosylation of isoform 2 of PKM (PKM2) (By similarity). Also acts as a S-nitroso-glutathione reductase by catalyzing the NADPH-dependent reduction of S-nitrosoglutathione. Displays no reductase activity towards retinoids (By similarity).
Synonyms: ALDR1; ALR; DD3; ARM; HEL-S-6
Tractability: Small molecule: a high-quality ligand is known; it has a high-quality binding pocket; it belongs to a druggable protein family. Antibody: UniProt places it where antibodies can reach, with medium confidence; its Gene Ontology location is reachable by antibodies, with medium confidence. PROTAC: ubiquitination databases record sites on it; its protein half-life has been measured; a small molecule that binds it is known.
Target class: Enzyme; Oxidoreductase
Gene: Protein-coding gene on chromosome 1 (45,550,475 to 45,570,051, forward strand). Ensembl gene ENSG00000117448.
Subcellular location: Cytoplasm, cytosol; Apical cell membrane
Subcellular location (Human Protein Atlas): Cytosol; Nucleoplasm
Pathways (Reactome):
Metabolism: Formation of xylulose-5-phosphate; Glutathione conjugation
Gene Ontology:
Molecular function: alcohol dehydrogenase (NADP+) activity; allyl-alcohol dehydrogenase activity; glucuronolactone reductase activity; glycerol dehydrogenase (NADP+) activity; L-glucuronate reductase activity; methylglyoxal reductase (NADPH) (acetol producing) activity; protein binding; S-nitrosoglutathione reductase (NADPH) activity; aldose reductase (NADPH) activity; all-trans-retinol dehydrogenase (NAD+) activity; aryl-alcohol dehydrogenase (NADP+) activity; oxidoreductase activity; S-nitrosoglutathione reductase (NADH) activity
Biological process: daunorubicin metabolic process; doxorubicin metabolic process; cellular detoxification of aldehyde; D-glucuronate catabolic process; glutathione derivative biosynthetic process; aldehyde catabolic process; negative regulation of apoptotic process
Cellular component: cytosol; extracellular exosome; extracellular region; apical plasma membrane; synapse
Genetic constraint (gnomAD): Loss-of-function variants: 26 observed, 41.44 expected, observed/expected ratio (o/e) 0.63, 90% interval 0.46 to 0.87. The upper end of that interval is the gene's LOEUF score, 0.87, which puts it in group 3 of 6, group 1 being the genes least tolerant of losing a copy. Missense variants: 378 observed, 429.75 expected, observed/expected ratio (o/e) 0.88, 90% interval 0.81 to 0.96. Synonymous variants: 141 observed, 163.36 expected, observed/expected ratio (o/e) 0.86, 90% interval 0.75 to 0.99.
Homologues: Orthologues: chimpanzee AKR1A1 (99% identical), macaque AKR1A1 (99% identical), rat Akr1a1 (94% identical), mouse Akr1a1 (93% identical), guinea pig AKR1A1 (92% identical), pig AKR1A1 (87% identical), rabbit AKR1A1 (81% identical), tropical clawed frog akr1a1 (74% identical), zebrafish akr1a1b (71% identical), Caenorhabditis elegans Y39G8B.1 (43% identical), Caenorhabditis elegans Y39G8B.2 (34% identical), Caenorhabditis elegans C01G5.5 (29% identical), and 5 more. Paralogues in human: AKR1B1 (50% identical), AKR1B10 (48% identical), AKR1D1 (44% identical), AKR1B15 (43% identical), AKR1C1 (43% identical), AKR1C2 (42% identical), AKR1C4 (42% identical), AKR1C8 (41% identical), AKR1E2 (41% identical), AKR1C3 (40% identical), AKR7A2 (27% identical), KCNAB2 (25% identical), and 4 more.
Diseases named in the same sentence as AKR1A1 in open-access papers:
AKR1A1 is named in the same sentence as 86 diseases in open-access papers, as found by Europe PMC text mining. Sharing a sentence is not in itself a finding about the gene and the disease. The quoted sentences say what the papers report.
breast carcinoma (8 papers, 2014 to 2025). "The polymorphic allele C of the AKR1A1 rs2088102 might act as a potential protective factor for chemotherapy in breast cancer patients." (PMID 40821701, 2025). "AKR1A1 is an aldehyde reductase that is associated with resistance to radiotherapy and chemotherapy in laryngeal cancer, breast cancer, etc.; however, there have been no similar studies for pancreatic cancer." (PMID 38268915, 2023).
alcoholic liver diseases (6 papers, 2013 to 2024). A disorder caused by damage to the liver parenchyma due to alcohol consumption. "Although previous studies found that AKR1A1 levels are decreased in the livers of patients with alcoholic liver disease, no research has further explored its correlation with the development of the disease." (PMID 38308335, 2024).
liver disease (3 papers, 2014 to 2024). "Furthermore, intense signals of 4-hydroxynonenal (4-HNE), a reliable biomarker of lipid peroxidation in liver diseases, were detected in the liver tissue sections of AF-treated Akr1a1−/− mice, whereas relatively weak signals were observed in the liver tissue of mice in the other groups." (PMID 38308335, 2024).
lung carcinoma (3 papers, 2015 to 2025). "Indeed, and just for example, we detected the upregulation of SERPB3 as well as the exclusive presence of S100A14 and AKR1A1 proteins in the saliva of this patient, which have already been implicated in LC and could represent potential lung cancer biomarkers." (PMID 40869249, 2025). "Previous studies showed that in human lung cell lines, AKR1C1 and AKR1A1 also play an important role in the metabolic activation of polycyclic aromatic hydrocarbons, a major component in PM2.5, which may contribute to the causation of human lung cancer." (PMID 26338969, 2015).
laryngeal carcinoma (2 papers, 2023 to 2024). Carcinoma that arises from the laryngeal epithelium.
liver cancer (2 papers, 2022). An epithelial or non-epithelial malignant neoplasm that arises from the liver. "Studies have shown that AKR1A1 can synthesize ascorbic acid in rodents and is involved in the metabolism of gamma-hydroxybutyric acid in human liver cancer-derived HepG2 cells." (PMID 35240026, 2022).
osteoporosis (2 papers, 2017 to 2025). A condition of reduced bone mass, with decreased cortical thickness and a decrease in the number and size of the trabeculae of cancellous bone (but normal chemical composition), resulting in increased fracture incidence. "Both GSEA and GSVA analyses consistently supported the potential regulatory role of AKR1A1 in the metabolic dysregulation underlying osteoporosis." (PMID 41246341, 2025). "This study systematically elucidates the multifaceted role of the lactylation-associated enzyme AKR1A1 in the pathogenesis of osteoporosis and, for the first time, proposes that it orchestrates disease progression through metabolic reprogramming, immune modulation, and intercellular communication." (PMID 41246341, 2025). "This study is the first to propose that AKR1A1-mediated lactylation is closely linked to metabolic reprogramming, thereby constructing a tripartite regulatory framework of “lactylation–metabolism–immunity” and offering a novel perspective on the metabolic pathology of osteoporosis." (PMID 41246341, 2025). "Our findings elucidate the involvement of AKR1A1 in the metabolic-immune regulatory axis of osteoporosis, providing both theoretical insights and experimental evidence for its potential as a therapeutic target." (PMID 41246341, 2025). "To date, no studies have systematically evaluated the lactylation status of AKR1A1 or its potential role in the metabolic-immune axis of osteoporosis pathogenesis." (PMID 41246341, 2025). "This conclusion addresses a critical knowledge gap regarding the lactylation of AKR1A1 and its regulatory role in the context of osteoporosis." (PMID 41246341, 2025). "This study identifies AKR1A1 as a key lactylation-modified gene involved in the pathogenesis of osteoporosis." (PMID 41246341, 2025). "AKR1A1 lactylation plays a pivotal role in the metabolic–immune regulatory axis of osteoporosis, contributing to metabolic reprogramming and immune microenvironment remodeling." (PMID 41246341, 2025). "Collectively, these findings suggest that AKR1A1 lactylation plays a central role in the metabolism–immunity regulatory axis of osteoporosis, and highlight its potential as an early molecular biomarker and therapeutic target." (PMID 41246341, 2025). "The Akr1A1 KO mice (Akr1A1eGFP/eGFP) exhibited insufficient serum ascorbic acid levels, abnormal bone development and osteoporosis." (PMID 28060768, 2017). "In conjunction with our findings, these results suggest that the lactylation of AKR1A1 may mediate its immunometabolic regulatory function, thereby playing a critical role in the pathogenesis of osteoporosis." (PMID 41246341, 2025). "On this basis, the development of selective small-molecule inhibitors targeting AKR1A1 lactylation could represent a novel therapeutic strategy for osteoporosis." (PMID 41246341, 2025). "Osteoporosis of the femur was the marked phenotype of the Akr1A1 KO mice." (PMID 28060768, 2017). "Therefore, through ascorbic acid administration, the Akr1A1 KO mice exhibited controllable osteoporosis and may serve as a novel model for osteoporotic research." (PMID 28060768, 2017). "This study, for the first time, links AKR1A1 lactylation—a candidate immunometabolic marker—to the SPP1–CD44-mediated bone marrow immune communication network, proposing the “AKR1A1–SPP1–CD44” axis as a novel signaling pathway involved in osteoporosis pathogenesis." (PMID 41246341, 2025).
ovarian carcinoma (2 papers, 2022). A malignant neoplasm originating from the surface ovarian epithelium. "It was discovered that upregulated mRNA of the AKR1C1–4 enzymes (originally known as dihydrodiol dehydrogenases) and AKR1A1 induces a resistance to cisplatin in human ovarian cancer cells." (PMID 35159076, 2022).
pancreatic cancer (2 papers, 2021 to 2023). "The mRNA expression levels of CSTF2, FAF2, KIF20B, AKR1A1, APOM, KRT6C, and CD70, which were included in the prognostic model, were detected in different types of pancreatic cancer cell lines." (PMID 38268915, 2023).
Sepsis (2 papers, 2025). Sepsis is defined as life-threatening organ dysfunction caused by a dysregulated host response to infection. "For instance, the glycerolipid metabolic gene Akr1a1, a cancer biomarker associated with mitochondrial metabolic activity, was down‐regulated across all tissues, again pointing to overall mitochondrial adaptation and dysfunction during sepsis." (PMID 40411399, 2025).
steatosis (2 papers, 2015 to 2024). Increased lipid within the cytoplasm of cells. "Stimulation by the mixture of palmitic acid and oleic acid (P/O), LPS, and TGF-β1 was used to mimic alcohol-induced steatosis, inflammation, and fibrosis, and Akr1a1 expression was knocked down by infection with a shRNA lentivirus targeting the Akr1a1 gene." (PMID 38308335, 2024). "Furthermore, in AML12 hepatocytes, Akr1a1 knockdown aggravated oxidative stress and steatosis induced by palmitic acid/oleic acid (P/O) inflammation induced by lipopolysaccharide (LPS), and fibrosis induced by TGF-β1." (PMID 38308335, 2024).
endometrial cancer (1 paper, 2025). Primary or metastatic malignant neoplasm involving the endometrium (mucous membrane that lines the endometrial cavity).
epilepsy (1 paper, 2023). A brain disorder characterized by episodes of abnormally increased neuronal discharge resulting in transient episodes of sensory or motor neurological dysfunction, or psychic dysfunction. "By correlating co-expressed genes as well as immune cell ratios, we obtained genes with significant correlation with immune cell ratios (SIRPA, AKR1A1, LEP, ALDOA) that will be validated in epilepsy data at the single cell level in an attempt to find immune genes that link heart and brain tissue." (PMID 36776884, 2023).
hypospadias (1 paper, 2020). Hypospadias is the displacement of the urethral meatus on the ventrum of the penis. "We further performed a colocalization analysis of primary pQTL and GWAS signals and found that the lead pQTL variant of AKR1A1 and HAAO were colocalized with the GWAS variants associated with blood protein levels and hypospadias, respectively." (PMID 32778093, 2020).
liver fibrosis (1 paper, 2024). "Next, liver fibrosis was examined by Masson’s trichrome and Sirius red staining, which showed that a particularly high amount of well-defined collagen fibers was found in the liver sections of AF-treated Akr1a1−/− mice." (PMID 38308335, 2024).
orchitis (1 paper, 2021). Inflammation of one or both testes due to viral or bacterial infections. "The level of key enzymes Ivd, Uqcrb, Sod1, Akr1a1, and Cat, which were members of the gene set Hallmark reactive oxygen species, were decreased during orchitis." (PMID 35111154, 2021).
schizophrenia (1 paper, 2021). A major psychotic disorder characterized by abnormalities in the perception or expression of reality. "Among the identified variants of AKR1A1 related to schizophrenia, the c.753G > A variant caused exon skipping, leading to the production of a truncated AKR1A1 protein." (PMID 34938315, 2021). "The AKR1A1 sequence was analyzed in patients with schizophrenia (n = 808) and control subjects (n = 636), and 28 variants were identified as a result." (PMID 34938315, 2021). "In the present study, we aimed to analyze genetic defects in AKR1A1 in patients with schizophrenia and identify the molecular mechanisms that cause the accumulation of GlucA." (PMID 34938315, 2021). "We identified 28 variants of AKR1A1 in patients with schizophrenia and control subjects." (PMID 34938315, 2021). "Therefore, the frameshift mutations in AKR1A1 might affect these metabolic processes, and thus may be related to the pathophysiology of schizophrenia." (PMID 34938315, 2021). "Here, we aimed to explore genetic defects in AKR1A1 in patients with schizophrenia, which may result in the accumulation of GlucA." (PMID 34938315, 2021).
cancer (22 papers, 2013 to 2025). A tumor composed of atypical neoplastic, often pleomorphic cells that invade other tissues. "Therefore, AKR1A1 can have both protective and detrimental effects in cancer." (PMID 40869249, 2025). "Thus, the actions of AKR1A1, whether anti-cancer or carcinogenic, appear to depend on the types of cells and also on the timing of the carcinogenic process." (PMID 34073440, 2021). "AKR1A1 is a member of the human aldo-keto reductase (AKR) family, which is widely distributed in most cancer cells with relatively stable abundances." (PMID 38843392, 2024). "AKR1A1, AKR1B1, and 13 other genes in STAD (TCGA, PanCancer Atlas) were analyzed using cBioPortal for Cancer Genomics." (PMID 36827074, 2023).
tumor (17 papers, 2014 to 2025). "Thereby, it seems that T24 may have originated from a patient with a molecular signature of downregulated AKR1A1 gene expression in the tumor cells." (PMID 32164285, 2020). "Furthermore, decreased levels of propylene glycol are indicative of dysregulated AKR1A1 gene expression in the tumor cells of urinary bladder, thus rendering it (propylene glycol) as a potentially significant biomarker." (PMID 32164285, 2020). "After tumor mutation profile and copy number variation (CNV) analyses, we established and validated a prediction model of KRAS mutations, based on survival analysis and mRNA expression, that contained seven genes: CSTF2, FAF2, KIF20B, AKR1A1, APOM, KRT6C, and CD70." (PMID 38268915, 2023). "Earlier study reported that SMAR1 acts as a tumor suppressor that involved in cell cycle regulation and inhibits AKR1A4 (the synonym of AKR1A1) via a direct interaction." (PMID 38308335, 2024). "The expression of MAOA, AKR1A1, ALDH9A1, HAAO, and ALDH2 was significantly downregulated in ESCC tumor tissues compared to non-tumor tissues." (PMID 40821701, 2025). "The results revealed that the expression of MAOA, AKR1A1, ALDH9A1, HAAO, and ALDH2 was significantly downregulated in ESCC tumor tissues compared to non-tumor tissues." (PMID 40821701, 2025).
AKR1A1 also shares sentences with these, for which no sentence is quoted: alcoholism (18 papers); infection (16); hepatocellular carcinoma (6); alcohol use disorder (4); alcoholic fatty liver disease (4); fungal infection (4); gastric cancer (4); alcohol fatty liver (3); Cirrhosis (3); colorectal cancer (3); Alzheimer disease (2); brain cancer (2); cardiovascular diseases (2); cognitive deficits (2); esophageal squamous cell carcinoma (2); head and neck squamous cell carcinoma (2); Hepatic (2); kidney damage (2); lactic acidosis (2); metabolic disorders (2); oral cancer (2); acute leukemia (1); alcoholic cirrhosis (1); allergic asthma (1); amnesia (1); anemia (1); ascorbic acid deficiency (1); atherosclerosis (1); brain tumour (1); Cerebral ischemia (1).
A further 37 diseases each share a sentence with AKR1A1 in 1 paper.